FGFR2 (fibroblast growth factor receptor 2)
Description:
Tyrosine-protein kinase that acts as a cell-surface receptor for fibroblast growth factors and plays an essential role in the regulation of cell proliferation, differentiation, migration and apoptosis, and in the regulation of embryonic development. Required for normal embryonic patterning, trophoblast function, limb bud development, lung morphogenesis, osteogenesis and skin development. Plays an essential role in the regulation of osteoblast differentiation, proliferation and apoptosis, and is required for normal skeleton development. Promotes cell proliferation in keratinocytes and immature osteoblasts, but promotes apoptosis in differentiated osteoblasts. Phosphorylates PLCG1, FRS2 and PAK4. Ligand binding leads to the activation of several signaling cascades. Activation of PLCG1 leads to the production of the cellular signaling molecules diacylglycerol and inositol 1,4,5-trisphosphate. Phosphorylation of FRS2 triggers recruitment of GRB2, GAB1, PIK3R1 and SOS1, and mediates activation of RAS, MAPK1/ERK2, MAPK3/ERK1 and the MAP kinase signaling pathway, as well as of the AKT1 signaling pathway. FGFR2 signaling is down-regulated by ubiquitination, internalization and degradation. Mutations that lead to constitutive kinase activation or impair normal FGFR2 maturation, internalization and degradation lead to aberrant signaling. Over-expressed FGFR2 promotes activation of STAT1.
Synonyms: KGFR; CD332; BEK; CEK3; TK14; TK25; ECT1; K-SAM; BBDS; BFR-1; CFD1; JWS
Tractability: Small molecule: an approved drug acts on it; a structure with a bound ligand is known; a high-quality ligand is known; it has a high-quality binding pocket; it belongs to a druggable protein family. Antibody: a drug acting on it is in phase 2 or 3 trials; its Gene Ontology location is reachable by antibodies, with high confidence; UniProt places it where antibodies can reach, with medium confidence; UniProt predicts a signal peptide or a membrane-spanning region. PROTAC: it is named in the literature on targeted protein degradation; UniProt records ubiquitination sites on it; ubiquitination databases record sites on it; its protein half-life has been measured; a small molecule that binds it is known. Other modalities: an approved drug acts on it.
Target class: Enzyme; Tyrosine protein kinase FGFR family; Protein Kinase; Kinase; TK protein kinase group
Chemical probes: AZD-4547 (high quality), DGY-09-192 (high quality), FIIN-1 (high quality), FIIN-2 (high quality), FIIN-3 (high quality), INFIGRATINIB (high quality), Lirafugratinib (high quality), PD134473
Gene: Protein-coding gene on chromosome 10 (121,478,332 to 121,598,458, reverse strand). Ensembl gene ENSG00000066468.
Subcellular location: Cell membrane; Golgi apparatus; Cytoplasmic vesicle; Cell membrane (Isoform 1); Cell membrane (Isoform 3); Secreted (Isoform 8); Secreted (Isoform 13)
Subcellular location (Human Protein Atlas): Cell Junctions; Nucleoplasm; Vesicles; Predicted to be secreted
Pathways (Reactome):
Signal Transduction: FGFR2 alternative splicing; FGFR2b ligand binding and activation; FGFR2c ligand binding and activation; FRS-mediated FGFR2 signaling; Negative regulation of FGFR2 signaling; PI-3K cascade:FGFR2; PI3K Cascade; PI5P, PP2A and IER3 Regulate PI3K/AKT Signaling; PIP3 activates AKT signaling; Phospholipase C-mediated cascade; FGFR2; RAF/MAP kinase cascade; SHC-mediated cascade:FGFR2
Disease: Activated point mutants of FGFR2; Constitutive Signaling by Aberrant PI3K in Cancer; Signaling by FGFR2 IIIa TM; Signaling by FGFR2 amplification mutants; Signaling by FGFR2 fusions; Signaling by FGFR2 in disease
Gene Ontology:
Molecular function: fibroblast growth factor binding; fibroblast growth factor receptor activity; protein binding; protein homodimerization activity; protein tyrosine kinase activity; ATP binding; protein kinase activity; transmembrane receptor protein tyrosine kinase activity
Biological process: embryonic cranial skeleton morphogenesis; fibroblast growth factor receptor signaling pathway; negative regulation of keratinocyte proliferation; peptidyl-tyrosine phosphorylation; positive regulation of cell population proliferation; positive regulation of MAPK cascade; positive regulation of phospholipase activity; protein autophosphorylation; angiogenesis; animal organ morphogenesis; axonogenesis; bone development; bone mineralization; bone morphogenesis; branch elongation involved in salivary gland morphogenesis; branching involved in labyrinthine layer morphogenesis; branching involved in prostate gland morphogenesis; branching involved in salivary gland morphogenesis; branching morphogenesis of a nerve; bud elongation involved in lung branching; cell fate commitment; cell-cell signaling; digestive tract development; embryonic digestive tract morphogenesis; embryonic organ development; and 76 more
Cellular component: cell cortex; cell surface; cytoplasm; nucleus; plasma membrane; excitatory synapse; membrane; receptor complex; cytoplasmic vesicle; extracellular region; Golgi apparatus
Genetic constraint (gnomAD): Loss-of-function variants: 18 observed, 96.04 expected, observed/expected ratio (o/e) 0.19, 90% interval 0.13 to 0.28. The upper end of that interval is the gene's LOEUF score, 0.28, which puts it in group 1 of 6, group 1 being the genes least tolerant of losing a copy. Missense variants: 682 observed, 1,082.7 expected, observed/expected ratio (o/e) 0.63, 90% interval 0.59 to 0.67. Synonymous variants: 382 observed, 402.4 expected, observed/expected ratio (o/e) 0.95, 90% interval 0.87 to 1.03.
Gene-disease validity (ClinGen):
ClinGen rates the evidence that FGFR2 causes each of these diseases.
Apert syndrome (autosomal dominant): Definitive. Apert syndrome (AS) is a frequent form of acrocephalosyndactyly, a group of inherited congenital malformation disorders, characterized by craniosynostosis, midface hypoplasia, and finger and toe anomalies and/or syndactyly.
Beare-Stevenson cutis gyrata syndrome (autosomal dominant): Definitive. A severe form of syndromic craniosynostosis, characterized by a variable degree of craniosynostosis, with cloverleaf skull reported in over 50% of cases, cutis gyrata, corduroy-like linear striations in the skin, acanthosis nigricans, skin tags, and choanal stenosis or atresia.
bent bone dysplasia syndrome 1 (autosomal dominant): Definitive.
Crouzon syndrome (autosomal dominant): Definitive. Crouzon disease is characterized by craniosynostosis and facial hypoplasia.
Pfeiffer syndrome (autosomal dominant): Definitive. Pfeiffer syndrome (PS) is a common form of acrocephalosyndactyly, a group of inherited congenital malformation disorders, characterized by variable degrees of bicoronal craniosynostosis, variable hand and foot malformations and various other associated manifestations.
LADD syndrome (autosomal dominant): Limited. A multiple congenital anomaly syndrome characterized by hypoplasia, aplasia or atresia of the lacrimal system; anomalies of the ears and hearing loss; hypoplasias, apalsias or atresias of the salivary glands; dental anomalies and digital malformations.
Cancer hallmarks: invasion and metastasis; escaping programmed cell death (promotes); proliferative signalling (promotes)
Homologues: Orthologues: mouse Fgfr2 (98% identical), chimpanzee FGFR2 (97% identical), macaque FGFR2 (97% identical), dog FGFR2 (94% identical), rat Fgfr2 (94% identical), pig FGFR2 (94% identical), guinea pig FGFR2 (92% identical), rabbit FGFR2 (92% identical), tropical clawed frog fgfr2 (78% identical), zebrafish fgfr2 (77% identical). Paralogues in human: FGFR1 (71% identical), FGFR3 (66% identical), FGFR4 (56% identical), KDR (31% identical), FLT1 (30% identical), FLT4 (29% identical), KIT (27% identical), CSF1R (27% identical), PDGFRA (26% identical), PDGFRB (26% identical), FLT3 (25% identical), TIE1 (24% identical), and 41 more.
Diseases named in the same sentence as FGFR2 in open-access papers:
FGFR2 is named in the same sentence as 464 diseases in open-access papers, as found by Europe PMC text mining. Sharing a sentence is not in itself a finding about the gene and the disease. The quoted sentences say what the papers report.
breast carcinoma (336 papers, 1997 to 2026). "Differences in panel performance influenced association signals, including breast cancer candidate loci such as FGFR2, TOX3, and ESR1." (PMID 41871294, 2026). "The exact mechanisms by which FGFR2 rs2981578 polymorphism jointly with demographic and lifestyle factors influence breast cancer development are complex and not yet fully understood." (PMID 40748883, 2025). "Meanwhile, a study also identified four additional SNPs in intron 2 of FGFR2 (rs11200014, rs2420946, rs1219648 and rs2981579) that linked to increased breast cancer susceptibility." (PMID 41318657, 2025). "Truncating FGFR2 exon 18 mutations, such as the FGFR2 frameshift variant seen in Tumor 3, are oncogenic and recurrent in cholangiocarcinoma and gastroesophageal and breast carcinoma and confer sensitivity to FGFR inhibition." (PMID 40906279, 2025). "FGFR2 rs2981578 is one of the 14 SNP of FGFR2 located in intron 2.FGFR2 rs2981578 was recognized as a genetic variant linked to breast cancer susceptibility in genome-wide studies (GWAS)." (PMID 40748883, 2025). "Mutations and alterations in the FGFR2 gene have been found to play a significant role in the development and progression of various types of cancer, including endometrial cancer, breast cancer, and gastrointestinal/genitourinary tract cancers." (PMID 39869563, 2025). "These variants boost silencer activity, reduce FGFR2 expression, and elevate the risk of breast cancer by increasing estrogen responsiveness." (PMID 40429751, 2025). "The current study aimed to determine the association between Fibroblast Growth Factor Receptor-2 rs2981578 single nucleotide polymorphism and breast cancer among female breast cancer patients." (PMID 40748883, 2025). "Many scholars have asserted that the FGFR2 gene is linked to an increased likelihood of breast cancer in American, African American, European, and Asian populations." (PMID 40748883, 2025). "High-risk breast cancer susceptibility was connected to the AA genotype and A allele of the FGFR2 rs2981578 G/A gene." (PMID 40748883, 2025). "Fibroblast Growth Factor Receptor-2 single nucleotide polymorphisms are implicated in breast cancer development." (PMID 40748883, 2025). "The study of the pathological characteristics of FGFR2 rs2981578 genotype groups in breast cancer patients has lifted the veil on potential links between FGFR2 rs2981578 variants and tumor histopathological features." (PMID 40748883, 2025). "The Fibroblast Growth Factor Receptor-2 Single Nucleotide Polymorphisms rs2981578 AA genotype and A allele were more frequent in breast cancer patients than in controls (37% vs. 17% and 58% vs 42%; the chi-square p = 0.025 and p = 0.009, respectively)." (PMID 40748883, 2025). "This study explores how FGFR2 rs2981578 SNP and various risk factors intersect in breast cancer among Ethiopians in Gondar, Amhara region." (PMID 40748883, 2025). "For instance, in an analysis of 4398 familial breast cancer cases and 4316 controls, five single-nucleotide polymorphisms (SNPs) (rs7895676, rs2912781, rs10736303, rs2912778 and rs2981582) in FGFR2 were found to be significantly associated with breast cancer." (PMID 41318657, 2025). "Multiple studies have explored the association between FGFR-2 rs2981578polymorphism and breast cancer across various patient populations." (PMID 40748883, 2025). "The AA genotype and the A allele of the Fibroblast Growth Factor Receptor-2 Single Nucleotide Polymorphisms rs2981578 gene are more prevalent among women with breast cancer." (PMID 40748883, 2025). "On the other hand, FGFR2 mutations serve as risk factors and increased breast cancer susceptibility." (PMID 39796710, 2024).
breast carcinoma (continued). "Genome-wide association studies on breast cancer have found a strong association with fibroblast growth factor receptor 2 (FGFR2)." (PMID 39596875, 2024). "Increased levels of FGFR2 and IIIb splice isoforms are associated with less aggressive breast cancer phenotypes, while decreased levels of FGFR2 and increased IIIc splice isoform are associated with more aggressive phenotypes." (PMID 39596875, 2024). "Online databases, including cBioPortal and TCGA SpliceSeq, were used to examine the association between the FGFR2 expression and splice variants with breast cancer subtypes." (PMID 39596875, 2024). "We identified FGFR2 to be significant via both expression- and splicing-based TWAS approaches and tissue with the max PIP was cultured fibroblasts (PIP = 1), indicating FGFR2 likely causally impacts breast cancer risk through its expression in fibroblasts." (PMID 38515142, 2024). "The upregulation of FGFR2 expression at protein level is associated with poor prognosis in human breast cancer." (PMID 38473753, 2024). "We performed in silico analyses to investigate the FGFR2 mRNA expression and splice variants associated with breast cancer subtypes." (PMID 39596875, 2024). "A previous study conducted among Jewish and Arab Israeli BC populations also described the genetic variations of the FGFR2 gene (including rs2981582 and rs2420946) as a risk factor for breast cancer." (PMID 37107577, 2023). "Several genome-wide meta-analyses show that single nucleotide polymorphisms (SNPs) in FGFR2 are strongly associated with an increased risk of breast cancer (BCa)." (PMID 37191822, 2023). "Our study found that FGFR2 genetic polymorphisms are significantly associated with breast cancer in Bangladeshi women." (PMID 37107577, 2023). "Fibroblast growth factor receptor 2 (FGFR2) gene polymorphisms are highly related to the risk of breast cancer." (PMID 37107577, 2023). "Despite these limitations, this study has provided a clear indication of the relationship between FGFR2 gene polymorphisms and the risk of breast cancer development in the Bangladeshi population." (PMID 37107577, 2023). "Two genes, MAP3K1 and FGFR2, in addition to being previously identified in breast cancer-associated genetic region in GWAS, are both classified as TIER1 cancer-driving genes in COSMIC Cancer Gene Census." (PMID 36703164, 2023). "Per institutional and public databases, FGFR2 mutations and amplifications had a population frequency of 1.1%–2.6% and 1.5%–2.5%, respectively, in breast cancer patients." (PMID 37980453, 2023). "This is the first study in Bangladesh that has looked at the association of FGFR2 polymorphisms with breast cancer and observed a significant outcome." (PMID 37107577, 2023). "Two of them, MAP3K1 and FGFR2, are long-established risk genes for breast cancer mediated by both germline and somatic mutations." (PMID 36703164, 2023). "Various studies revealed their relevance to breast cancer risk, where a polymorphism occurred in the FGFR2 intron 2 location and modulated the interaction of two transcription factors named Oct-1/Runx2 and C/EBPb." (PMID 37107577, 2023). "Next, we focused on fibroblast growth factor receptor 2 (Fgfr2), which has been implicated in the breast cancer formation 23-26." (PMID 37063417, 2023). "They found that genetic variants in FGFR2 (rs2981582 C > T, rs1219648 A > G, and rs2420946 C > T) were associated with breast cancer risk." (PMID 37107577, 2023). "This case–control study was performed to clarify the association between breast cancer and three common FGFR2 polymorphisms (rs1219648, rs2420946, and rs2981582) in the Bangladeshi population." (PMID 37107577, 2023). "Considering this fact, the current case–control study was performed to clarify the potential relationship between breast cancer and three common FGFR2 polymorphisms (rs1219648, rs2420946, and rs2981582)." (PMID 37107577, 2023).
breast carcinoma (continued). "The importance of the FGF/FGFR system in breast cancer is additionally reinforced via genome-wide association studies where common genetic variation in the FGFR2 locus is robustly associated with breast cancer." (PMID 37546410, 2023). "FGFR2 has been suggested to be implicated in breast cancer as a target for therapeutic strategies, CCND1 is frequently mutated by copy number variation and suggested as a prognostic biomarker." (PMID 35267517, 2022). "Genome-Wide-Association-Studies (GWAS) have shown that SNPs in the second intron of the FGFR2 gene are significantly associated with high risk of breast cancer, in particular in post-menopausal women, confirming an oncogenic role for FGFR2." (PMID 35193394, 2022). "Translating these interactions helped explain the association of this SNP with FGFR2 gene regulation in breast cancer." (PMID 35176995, 2022). "Since then, genome-wide association studies have associated SNPs within the FGFR2 gene with increased breast cancer susceptibility." (PMID 35193394, 2022). "For example, three variants identified in early GWAS for overall breast cancer, FGFR2 (rs35054928 and rs2981578) and 8q24.21 (rs13281615), were associated with luminal-like and HER2-positive/non-luminal subtypes, but not with TN disease." (PMID 34983606, 2022). "FOXA1 is highly associated with breast cancer with a score of 5.8 and was identified as one of the master regulators of FGFR2." (PMID 35176995, 2022). "A study demonstrated that single-nucleotide polymorphisms in FGFR2 reduce the expression of FGFR2 and increase cell sensitivity of breast cancer towards estrogen." (PMID 36601474, 2022). "GWAS data revealed the association between FGFR2 genetic variants and the risk of breast cancer, for instance, rs4752575 was shown to alter the expression of FGFR2 leading to the increased susceptibility to breast cancer." (PMID 35176995, 2022). "A potential mechanism for this implies FGFR2-dependent increase in the binding of two transcription factors associated with high-risk breast cancer, NFIB and YBX1, to the ER in the nucleus." (PMID 35193394, 2022). "FGF10 expression increases if the rs10941679 SNP is present, which in turn would increase risk of breast cancer in patients expressing the FGFR2 SNP rs2981578 variant." (PMID 35193394, 2022). "FGFR2 signaling plays a role in cancer-associated fibroblast-dependent breast cancer resistance to TAM." (PMID 36601474, 2022). "In fact, such a variant missing the inhibitory carboxyl terminal portion of FGFR2 was expressed in a breast cancer cell line (SUM-52PE), along with other splice variants, with the different splice variants having different transforming activities." (PMID 34830836, 2021). "Genome-wide association studies analyzing 4,398 cases with familial breast cancer causes and 4,316 controls identified five single-nucleotide polymorphisms of FGFR2 significantly associated with breast cancer." (PMID 33462336, 2021). "More recently another study identified an FGFR2 SNP that was linked with susceptibility to breast cancer in a Chinese population." (PMID 34830836, 2021). "Risk alleles of various SNPs found in FGFR2, they are associated with ER-positive cancers, increased FGFR2 expression, lymph node metastasis in breast cancer and radiation-induced breast cancer risk." (PMID 34830836, 2021). "Lastly, SigMod missed some of the highest scoring breast cancer susceptibility genes in the dataset, like FGFR2 and TOX3." (PMID 33735170, 2021). "FGFR2 overexpression occurred in both the TNBC/basal and luminal subtypes and was rarely observed in HER2 cancers, while 19 breast cancer patients (1.9%) exhibited mutation or fusion of FGFR2 in the TCGA dataset." (PMID 34344433, 2021). "The missense mutations of the FGFR2 gene occur in endometrial cancer, cervical cancer, breast cancer, lung cancer, and GC." (PMID 34307360, 2021).